LDHB (lactate dehydrogenase B)
Diseases named in the same sentence as LDHB in open-access papers (continued):
Sharing a sentence is not in itself a finding about the gene and the disease.
melanoma (15 papers, 2011 to 2025). A malignant, usually aggressive tumor composed of atypical, neoplastic melanocytes. "On the functional level, the double-knockout of LDHA and LDHB rendered murine melanoma and human colorectal adenocarcinoma cells more sensitive to RT7." (PMID 40158058, 2025). "By machine learning algorithms, we identified 6 key CRGs (ABCC2, CA14, EGR3, FBXW7, LDHB, and PSEN2) closely associated with melanoma." (PMID 39213172, 2024). "For example, B16F10 melanoma cells were still able to secrete substantial amounts of lactate following the elimination of either LDHA or LDHB alone." (PMID 37868977, 2023). "Like in the case of ATP5A1, LDHB expression was detected predominantly in the cytoplasm of melanoma cells." (PMID 23043612, 2012). "The absence of increased LDH5 in patients with high serum LDH can be explained by the significant positive correlation between LDHA and LDHB expression in melanomas and that more LDHB than LDHA proteins are upregulated in advanced melanomas." (PMID 23043612, 2012). "We identified 5 melanoma-associated antigens using this microarray coupled to mass spectrometry; GRP75, GRP94, ASAH1, CTSD and LDHB." (PMID 22084687, 2011). "LDHB can provide energy for melanoma cell growth through the glycolysis pathway, and its high expression could lead to poor prognosis of melanoma patients." (PMID 39213172, 2024). "Furthermore, LDHA/LDHB deficiency also diminished glycolysis and STING activation in tumor-infiltrating DCs and impaired DC antitumor immunity in B16-F10 melanoma model." (PMID 36821379, 2023). "Additionally, GNE-140, which targets both LDHA and LDHB, was sufficient to mimic the effect of the simultaneous elimination of both isoforms in melanoma cells in terms of inhibition of glycolysis and reactivation of oxidative phosphorylation in WT cells." (PMID 37868977, 2023). "Finally, our new analysis method identified NNMT and LDHB, which would otherwise be missed in conventional analysis, as novel target genes whose ablation sensitizes melanoma cells to vemurafenib." (PMID 36829149, 2023). "Our findings align with a previous study in which double knockout of LDHA and LDHB in human colon adenocarcinoma (LS174T) and murine melanoma (B16-F10) cells led to a two-fold reduction in growth rates compared to wild-type cells." (PMID 41279318, 2025). "This study aimed to disrupt the energy metabolism within melanoma tumors by targeting LDH enzymes, specifically LDHA and LDHB, with the goal of enhancing the efficacy of ICI treatments." (PMID 39435293, 2024). "Among them, 4 key CRGs (ABCC2, CA14, LDHB, PSEN2) were significantly upregulated and 2 key CRGs (EGR3, FBXW7) were significantly downregulated in melanoma tissues." (PMID 39213172, 2024). "Six CRGs (ABCC2, CA14, EGR3, FBXW7, LDHB, and PSEN2) were identified as key CRGs for melanoma diagnosis and prognosis." (PMID 39213172, 2024). "Compared to normal skin tissues, 4 key CRGs (ABCC2, CA14, LDHB, PSEN2) were significantly upregulated while 2 key CRGs (EGR3, FBXW7) were significantly downregulated in melanoma tissues." (PMID 39213172, 2024). "Melanoma cells, however, stopped proliferating under hypoxic conditions following the simultaneous elimination of both LDHA and LDHB." (PMID 37868977, 2023). "Finally, by comparing the feature genes identified by the three machine learning approaches, six common key CRGs were identified as melanoma-related key CRGs, including ABCC2, CA14, EGR3, FBXW7, LDHB, and PSEN2." (PMID 39213172, 2024). "Specifically, high expression of 4 key CRGs (ABCC2, CA14, LDHB, PSEN2) was significantly correlated with poor prognosis in melanoma patients (HR>1, P<0.05), while low expression of 2 key CRGs (EGR3, FBXW7) was significantly associated with poor prognosis (HR<1, P<0.05)." (PMID 39213172, 2024).
melanoma (continued). "This aligns with recent findings suggesting that both LDHA and LDHB contribute to pyruvate-to-lactate conversion, requiring the simultaneous knockout of both LDHA and LDHB to stop lactate production in LS174T (human colorectal adenocarcinoma) and B16-F10 (mouse melanoma) cell lines." (PMID 39435293, 2024). "Interestingly, data from a recent study suggest that LDHB expression is required for energy metabolism in hypoxia, as knockout of both LDHA and LDHB were required to restrict growth of human colon cancer and mouse melanoma cell lines." (PMID 37107600, 2023). "However, the LDHB expression did not change in LDHA knockout mouse melanoma (B16-F10) cells, as analyzed using Western blotting." (PMID 31921691, 2019). "LDHB, but not ATP5A1, expression was significantly increased in advanced melanomas compared with nevi (Poisson model LRT p < 0.001 and p = 0.098, respectively)." (PMID 23043612, 2012).
prostate carcinoma (15 papers, 2015 to 2025). A carcinoma that arises from epithelial cells of the prostate gland. "TUFM and ACPP, which are frequently associated with prostate cancer, and two metabolic enzymes, LDHB and OXCT1, were further confirmed at the protein level in DHT (androgen)- and FSK (PKA signaling)-stimulated VCaP cells by immunoblotting." (PMID 34680521, 2021). "In this study, we found increased expression of LDHB in androgen-stimulated VCaP cells (right), supporting the prognostic and diagnostic value of LDHB as well as its role as a therapeutic target in prostate cancer." (PMID 34680521, 2021). "A previous study showed that loss of LDHB expression in prostate cancer was due to promoter hypermethylation." (PMID 31316912, 2019). "Aberrant activation of the FGFR1 signaling pathway is sufficient to enhance the Warburg effect through differential regulation of LDHA and LDHB in prostate cancer." (PMID 33390837, 2021). "In conclusion, P5C released by prostate cancer cells inhibits the glycolysis of T cells in the tumor microenvironment via SHP1, PKM2 and LDHB complexes." (PMID 38326896, 2024). "Previous studies in prostate cancer demonstrated that STAT1 could enhance tumor progression through transcriptional regulation of LDHA and LDHB, highlighting its significant role in metabolic regulation 32, underscoring its role in metabolic regulation." (PMID 41208879, 2025). "Our study indicated that the protein expression of three markers (FGFR1, LDHB, and MYPT1) were correlated with prostate cancer patients' outcomes (biochemical recurrence) in tumor-adjacent stroma, and such correlations were surprisingly opposite to those in tumor tissues." (PMID 31316912, 2019).
triple-negative breast carcinoma (15 papers, 2015 to 2025). An invasive breast carcinoma which is negative for expression of estrogen receptor (ER), progesterone receptor (PR), and human epidermal growth factor receptor 2 (HER2). "In contrast, in triple-negative breast cancer cells, increased LDHB expression is observed, and associations between LHDB overexpression and unfavorable prognosis were demonstrated." (PMID 30967137, 2019). "In basal-like or triple-negative breast cancer, LDHB was highly expressed and associated with poor outcomes." (PMID 25973606, 2015). "BACH1 inhibits the expression of monocarboxylate transporter 1 (MCT1, encoded by SLC16A) and lactate dehydrogenase B (LDHB), downregulating lactate utilization in triple-negative breast cancer (TNBC) cells." (PMID 38321558, 2024). "As a key enzyme in the glycolysis pathway, LDHB is also an essential protein for triple-negative breast cancer." (PMID 36059961, 2022). "LDHB and other related glycolysis enzymes are significantly upregulated in triple-negative breast cancer." (PMID 36059961, 2022). "LDHB is upregulated in triple-negative breast cancer cells and its knockdown reduced cell proliferation." (PMID 34158867, 2021). "Another high expressing transcript includes LDHB, which is involved in triple negative breast cancer." (PMID 28086829, 2017). "LDHB is associated with glycolytic phenotypes in triple-negative breast cancer and KRAS-dependent lung adenocarcinomas, in which LDHB is the predominant form for glycolysis." (PMID 25973606, 2015). "Furthermore, the level of LDHB predicted a pathologically complete response to anthracycline-based neoadjuvant chemotherapy in both HR-positive/HER2-negative and triple-negative breast cancers." (PMID 25973606, 2015).
glioma (13 papers, 2016 to 2025). A benign or malignant brain and spinal cord tumor that arises from glial cells (astrocytes, oligodendrocytes, ependymal cells). "The observation that inhibitors block EV homing provides novel insights into many therapeutic opportunities to target LDHA/LDHB in glioma treatment." (PMID 40093910, 2025). "The same tendency was observed when the expression of LDHA and LDHB was analyzed in low‐grade gliomas." (PMID 36278433, 2022). "The elevated levels of LDHB in IDH1MUT gliomas support the findings in previous studies that showed that IDH1MUT glioma have reduced intracellular lactate levels compared to IDH1WT glioma." (PMID 28467784, 2017). "Our results also support previous reports that show that IDH1MUT gliomas silence LDHA expression through hypermethylation of its promoter resulting in a low LDHA/LDHB ratio compared with IDH1WT glioma or normal brain tissue." (PMID 28467784, 2017). "The expression levels of HIF-1α and LDHB were found to be increased in high-grade gliomas compared with low-grade gliomas." (PMID 26735579, 2016). "Interestingly, Wu found that LDHB expression was lower in glioma, and LDHB was identified as a protective factor using Chinese Glioma Genome Altas (CGGA) and TCGA databases." (PMID 37547725, 2023). "Finally, the increased expression of LDHB in mutIDH1R132H glioma, the enzyme that converts lactate to pyruvate, is also of interest." (PMID 35028610, 2021). "It has been shown in in silico studies that IDH1-mutant gliomas have significantly higher lactate dehydrogenase B expression comparing to wild-type tumours; and higher lactate oxidation was hypothesised in IDH1 mutation bearing cells." (PMID 30404651, 2018). "Conversely, IDH1MUT glioma showed higher LDHB expression levels than IDH1WT glioma." (PMID 28467784, 2017). "The results showed that glioma tissues have higher expression of LDHA, HLF1A, SLC16A1, and MRS2 and lower expression of LDHB and SLC25A12 compared with paracancerous tissues." (PMID 36698888, 2022). "Silencing the LDHB gene with small interfering RNA has been shown to reduce cell growth in a number of cancer cell lines, including WT IDH1 glioma." (PMID 35028610, 2021). "Taken together, we show that relative to IDH1WT glioma, IDH1MUT glioma use lactate and glutamate (but lesser so glutamine) for the TCA cycle, by maintaining high expression of LDHB, PC and GLUD and silencing BCAT." (PMID 28467784, 2017). "Our study showed that LDHA, MRS2, and SLC16A1 were indicators of poor survival, while LDHB and SLC25A12 were indicators of favorable prognosis, suggesting that lactate metabolism is dysregulated in glioma and this dysregulated expression is closely related to tumor progression." (PMID 36698888, 2022). "LDHA, which catalyzes oxidation of pyruvate to lactate, is downregulated in mutIDH1R132H glioma cells, PDX (mouse), and PTBs,213,217,218 whereas LDHB (which converts lactate to pyruvate) has increased expression in mutIDH1R132H-expressing BT142 cells, PTBs, and PDX (mouse) gliomas." (PMID 35028610, 2021). "Results indicated a marked upregulation of LDHA at both mRNA and protein levels in LN229 and U87MG cells, whereas LDHB was significantly expressed in U251MG and SW1783 cells at both mRNA and protein levels, highlighting differential LDH subunit expression across these glioma cell lines." (PMID 39895794, 2025).
lung adenocarcinoma (13 papers, 2015 to 2025). A carcinoma that arises from the lung and is characterized by the presence of malignant glandular epithelial cells. "Our in silico analysis of single-cell sequencing data from human breast and lung adenocarcinoma tumors as well as from human pancreatic normal tissue further revealed the existence of distinct subpopulations, which feature either high LDHB or GPX4 expression but rarely both together." (PMID 40090955, 2025). "Furthermore, increased LDHB expression in lung adenocarcinomas was significantly correlated with enriched expression of genes associated with the DNA damage response, such as DNA repair, cell cycle, and purine/pyrimidine biosynthesis." (PMID 40158058, 2025). "Our in silico analysis revealed that LDHB expression was higher in tumor tissue than in normal tissue in both lung adenocarcinoma (LUAD) and squamous cell carcinoma (LUSC) and increased LDHB expression in LUAD correlated with poor patient survival." (PMID 35877003, 2022). "For example, LDHB is overexpressed and required for the growth of KRAS-dependent lung adenocarcinomas." (PMID 26426634, 2015). "In addition, our analysis of TCGA data on lung adenocarcinoma revealed that elevated expression of hypoxia-inducible factor 1A (HIF1A), lactate dehydrogenase A (LDHA), lactate dehydrogenase B (LDHB) and SLC16A1 is significantly correlated with poor prognosis." (PMID 34150616, 2021).
hepatocellular carcinoma (11 papers, 2012 to 2025). A malignant tumor that arises from hepatocytes. "Likewise, high LDHB expression is associated with a favorable prognosis in patients with hepatocellular carcinoma, urothelial carcinoma, and prostate cancer." (PMID 36551514, 2022). "However, the association between LDHB expression and the clinicopathological characteristics of hepatocellular carcinoma (HCC) is not well understood." (PMID 26426634, 2015). "In several cancers, including prostate, bladder, and hepatocellular carcinoma, LDHB is silenced due to promoter methylation." (PMID 40790017, 2025). "June-Hyungkim, while working on hepatoma cells, reported that lactate dehydrogenase B (LDHB) plays a compelling role in the process of invasiveness of hepatoma cells by activating the tight junction protein claudin-1 (Cln-1)." (PMID 36761981, 2023). "On the other hand, suppression of LDHB expression promoted the progression of pancreatic cancer and the unfavorable survival of patients with hepatocellular carcinoma." (PMID 36551514, 2022). "It is reported that lactate dehydrogenase B (LDHB) suppression leads to hepatoma cell invasiveness via inducing CLDN1 expression." (PMID 35008557, 2021). "However, while decreased LDHB levels were reported in prostate, bladder, and hepatocellular carcinomas, an increased LDHB expression was described in lung and pancreatic adenocarcinomas, non-small-cell lung cancer and osteosarcoma." (PMID 31086659, 2019). "All three human cancer cell lines showed silenced LDHB expression compared to human normal liver THLE3 cells and mouse hepatoma Hepa1-6 cells also showed silenced LDHB expression compared to mouse normal liver tissue." (PMID 38739169, 2024). "However, the role of LDHB in modulating immune responses against hepatocellular carcinoma (HCC) remains largely unknown." (PMID 38739169, 2024). "However, a recent study showed that overexpression of LDHB suppressed hepatocellular carcinoma growth in immunocompetent but not in immunodeficient mice, suggesting that the host immune system was involved in the LDHB-medicated tumor suppression." (PMID 40790017, 2025).
gastric cancer (10 papers, 2012 to 2023). A primary or metastatic malignant neoplasm involving the stomach. "An integrated transcriptomic and proteomic analysis revealed that TIIA at 5.3 μM reduced glucose consumption and the production of ATP and pyruvic acid by down-regulating the expression of glucose-6-phosphate isomerase (G6PI) and LDHB in AGS gastric cancer cells." (PMID 36438836, 2022). "After treatment with paeonol at 60 mg/L, the levels of GLUT1, LDHB, and HK2 proteins in gastric cancer cells decrease markedly, and aerobic glycolysis is significantly weakened." (PMID 36438836, 2022). "Moreover, recent studies have shown decreased expression or even absence of the LDHB subunit, the enzyme converting lactate into pyruvate, in breast, prostate and gastric cancers due to hyper-methylation of the LDHB promoter." (PMID 26099350, 2016).
breast tumors (8 papers, 2015 to 2024). "Decreased LDHB expression in breast tumor cells causes NK cell activation and promotes tumor progression." (PMID 38739169, 2024). "An association between E-cadherin variant and LDHB levels was also demonstrated through the analysis of both transcripts in 21 human breast tumor samples." (PMID 31086659, 2019). "Quantitative expression analysis of E-cadherin variant and LDHB by real time PCR in 21 human breast tumor tissues." (PMID 31086659, 2019). "Finally, a positive association between expression levels of the E-cadherin variant and LDHB transcripts was demonstrated in 21 human breast tumor tissues, and breast tumor samples with higher Ki67 expression showed higher LDHB mRNA levels." (PMID 31086659, 2019). "80% of the breast tumor samples with low E-cadherin variant mRNA expression showed low levels of LDHB mRNA, while 81.82% of the samples with high E-cadherin variant expression levels presented high LDHB mRNA expression." (PMID 31086659, 2019). "As result of this analysis, breast tumor tissues from the Ki-67 ≥ 20% group showed higher LDHB transcript expression levels than those from the Ki-67 < 20% group." (PMID 31086659, 2019). "Patients with elevated LDHB levels in breast tumors show a poor clinical outcome." (PMID 32350346, 2020). "However, in triple negative/basal-like breast tumors, LDHB is increased." (PMID 33668689, 2021). "The downstream genes of lactate catabolic pathways, LDHA and LDHB, also showed potential inverse correlations with BACH1 expression in breast tumors." (PMID 35406740, 2022). "Next, we analyzed breast tumor data from the Cancer Genome Atlas (TCGA) patient cohorts (n = 980) for BACH1, MCT1, and LDHB mRNA expression." (PMID 35406740, 2022).
colon cancer (7 papers, 2011 to 2025). "It has been shown that the maintenance of low pyruvate level in colon cancer cells caused by the silencing of LDHB and the up-regulation of LDHA resulted in avoidance from cell death." (PMID 22363243, 2011). "SIRT5 can bind to LDHB and promote LDHB enzyme activity by deacetylating lysine 329 on LDHB, thereby enhancing autophagy and accelerating the growth of colon cancer cells." (PMID 39778006, 2025). "Furthermore, immuno-histochemical staining of consecutive tumor sections showed that Aurora-A and LDHB are simultaneously overexpressed in colon cancers." (PMID 31804482, 2019). "RPS7 is also down-regulated in colon cancer and its overexpression is correlated with good prognosis as it suppresses hypoxia-inducible transcription factor-1α (HIF-1α), metabolic promoting proteins glucose transporter 4 (GLUT4) and lactate dehydrogenase B (LDHB) both in vitro and in vivo." (PMID 34873618, 2021).